ABCB1 (ATP binding cassette subfamily B member 1)
Diseases named in the same sentence as ABCB1 in open-access papers (continued):
Sharing a sentence is not in itself a finding about the gene and the disease.
cancer (continued). "Overall, our findings suggest that furmonertinib effectively countered MDR in cancer cells overexpressing ABCB1 or ABCG2, achieved through the inhibition of drug efflux activity for both transporters, rather than by inducing changes in the protein expression of ABCB1 and ABCG2." (PMID 37762275, 2023). "More importantly, the efficacy of HS-173 in multidrug-resistant cancer cells could be recovered by inhibiting the drug-efflux function of ABCB1 and ABCG2." (PMID 37048130, 2023). "Therefore, identifying novel ABCB1 inhibitors is urgently needed to reverse the MDR in cancer cells." (PMID 37513931, 2023). "In addition, P-gp/(ABCB1) plays a main role in the multidrug-resistant phenotype in cancer mediating MDR." (PMID 36662632, 2023). "Overexpression of ABCB1 has been identified in a wide range of multidrug-resistant cancers." (PMID 37686513, 2023). "It is still not fully understood how exactly this single nucleotide change is able to impact the stability of the ABCB1 mRNA, and more research needs to focus on understanding this in normal tissues before we can move on to trying to understand its role in cancer chemotherapy resistance." (PMID 37686513, 2023). "ABCB1 can become upregulated in many ways, and understanding these mechanisms of upregulation could provide novel insights into cancer multidrug resistance." (PMID 37686513, 2023). "In this review, we summarize genetic and epigenetic mechanisms of ABCB1 upregulation in cancer and highlight areas that may be relevant for future research." (PMID 37686513, 2023). "A critical mechanism for evading chemotherapeutic toxicity is the overexpression of ABCB1 protein or P-glycoprotein (P-gp) on their membranes and the active pumping of chemotherapeutic drugs as substrates from cancer cells to reduce their intracellular toxicity." (PMID 37176096, 2023). "Gene amplification, alternative promotors, and multiple transcription start sites are important ABCB1 regulators in the context of bacterial antibiotic resistance and cancer multidrug resistance; their role at the blood-brain barrier is unknown." (PMID 36973040, 2023). "2-Aminoimidazole marine alkaloids have various biological activities, including anti-cancer, antimicrobial, antivirus properties, ABCB1-mediated MDR reversal activity as well as both leukotriene B4 receptor and epidermal growth factor (EGF) receptor antagonist activities." (PMID 37233508, 2023). "Indeed, it is reported that vemurafenib is a substrate of P-glycoprotein and BCRP (breast cancer resistance protein, ABCG2); therefore, ABCB1 overexpression in the cancer cells can simply avoid intracellular accumulation and activity of vemurafenib." (PMID 37508582, 2023). "The literature suggests that the 28 exon ABCB1 is most commonly produced by normally functioning cells, whereas drug-resistant cancer cells might more frequently produce the slightly longer 29 exon form." (PMID 37686513, 2023). "However, as previously shown, patients with lung tumour present a similar level of ABCB1 expression in cancer tissue and blood cells." (PMID 36755808, 2023). "Overexpression of the GCS enzyme has also been linked to increased expression of the ABCB1 lipid transporter protein (also called P-glycoprotein and encoded by the MDR1 gene) in several cancer cell types, which leads to increased anticancer drug efflux and multidrug resistance." (PMID 35756630, 2022). "Hence, overexpression of ABCB1 in cancer cells decreases intracellular concentrations of these drugs and produces MDR." (PMID 36439493, 2022). "In this way we could assess the specific expression of ABCB1 protein (P-gp) in cancer cells, as well as the relative expression of the membrane-bound functional drug transporter." (PMID 35721223, 2022). "ABCB1 participates in the transportation of anticancer drugs, such as doxorubicin, etoposide, paclitaxel, and vinblastine, playing an essential role in the multidrug resistance phenotype of cancer cells." (PMID 35372014, 2022).
cancer (continued). "Currently, whether CDK4 and/or CDK6 have direct regulatory effects on ABCB1 and ABCB1-mediated MDR in cancer, their roles, and mechanisms are unknown." (PMID 35459184, 2022). "Moreover, overexpression of ABCB1 in cancer cells can confer resistance to tyrosine kinase inhibitors (TKIs) such as imatinib and dasatinib." (PMID 35327403, 2022). "ABCB1 expression may also contribute to the side population cell isolation from the 769P cell line and serve as a mediator in the cancer stem cell pathogenesis of ccRCC." (PMID 35865926, 2022). "Moreover, in the PTCSC3-overexpressing cell lines, Prominin 1 (PROM1) and ATP-binding cassette subfamily B member 1 (ABCB1) expression levels, two cancer stem-cell markers, were found to be diminished." (PMID 35804851, 2022). "Several mechanisms have been identified to regulate the expression of ABCB1 in cancer cells." (PMID 36233525, 2022). "Among them, FOS-promoting cell autophagy was upregulated, whereas PI3K (PIK3CA/PIK3CB), which is a key signaling factor in cancer and was found to regulate ABCB1-mediated MDR in our recent study, was downregulated accompanying the remarkable downregulation of ABCB1." (PMID 35459184, 2022). "Among 49 identified members, P-glycoprotein (ABCB1), breast cancer resistance protein (ABCG2) and MDR-associated protein 1 (ABCC1) have been well-clarified to play critical roles in the promoting MDR phenomenon in cancer." (PMID 36559089, 2022). "For example, IM reversed the resistance to Dox in ABCB1-overexpressing cancer cells." (PMID 35327403, 2022). "In this study, we surveyed the connection of ARS-1620 with ABCB1-overexpressing cancer cells and we found that the overexpression of ABCB1 confers resistance to ARS-1620, which may affect its effectiveness in clinical anticancer treatments." (PMID 35281897, 2022). "Our findings show that rhMG53 when combined with doxorubicin exerts an anti-cancer effect on both parental and ABCB1 overexpressing tumors without any apparent weight loss or hematological toxicity." (PMID 36147477, 2022). "Consequently, targeting ABC transporters, such as ABCB1, to overcome drug resistance in cancer patients has been explored in clinical trials in various cancer entities." (PMID 36614114, 2022). "Our previous study revealed that P110α and P110β could be potential targets that regulate ABCB1-mediated MDR in cancers." (PMID 35459184, 2022). "This study revealed the cross downregulation between CDK6 and PI3K in cdk6 deficient cancer cell populations, demonstrated that CDK6-PI3K axis could be new target for inhibiting ABCB1-mediated MDR." (PMID 35459184, 2022). "Due to the intricacy of the function of ribociclib within the MDR cancer cells, specific gene deletion was performed to analyze whether CDK6 could be an effective target for overcoming ABCB1-mediated MDR in cancer cells." (PMID 35459184, 2022). "In addition, MDR can also be attributed to the overexpression of ABC transporters in cancer cells, such as ABCB1 (also known as P-glycoprotein (P-gp))." (PMID 35957103, 2022). "therefore, realizing downregulation of PIK3CA and ABCB1 by knocking out CDK6 in MDR cancer cells overexpressing ABCB1 might benefit combined chemotherapy against cancer cells with ABCB1-mediated MDR." (PMID 35459184, 2022). "Cancer cells treated with Doxorubicin stimulate the secretion of EVs enriched in the protein ATP-binding cassette sub-family B member 1 (ABCB1), a transporter involved in promoting the efflux of chemotherapeutic drugs, by the upregulation of Rab8B and downregulation of Rab5 proteins." (PMID 35646668, 2022). "The MDR-ABC transporter most studied in cancer is P-glycoprotein (P-gp, ABCB1)." (PMID 36142724, 2022). "Indeed, in the present study, the sensitivity to eribulin was associated with the ABCB1, ABCC1, p-AKT, p-NFκB, and NFκB expression levels in the blood cancer cells." (PMID 36551566, 2022). "The cytotoxicity of ARS-1620 on ABCB1-overexpressing cancer cells." (PMID 35281897, 2022).
cancer (continued). "In one of the studies on KBV200 and HCT-8/V cancer cells, it was shown that targeting and knocking out the ABCB1 gene using CRISPR/Cas9 technology significantly increased the accumulation of doxorubicin (DOX) inside the cells and significantly enhances chemosensitivity." (PMID 35715750, 2022). "As ABCB1 is a vital ABC transporter for the cancer cells to extrude a variety of anti-cancer drugs, we investigated the targets to reverse ABCB1-mediated MDR based on screening of effective reversal agents and gene deletion technology, and revealed a novel targeting pathway." (PMID 35459184, 2022). "A very limited number of studies estimated the impact of ABCB1 gene polymorphisms on Dox pharmacokinetics and pharmacodynamics, although the role of the ABCB1/MDR1 transporter in the regulation of intracellular concentration of anti-cancer agents and their therapeutic effects were reported." (PMID 36358854, 2022). "Moreover, these EVs transfer ABCB1 to sensitive cancer cells and confer a transient drug-resistant phenotype by downregulation of Rab5 in the recipient cell." (PMID 35646668, 2022). "ABCB1 is regulated by N6-methyladenosine-induced ERRγ and triggers chemoresistance in cancer cells." (PMID 35874705, 2022). "Known non-canonical Notch targets include YY-1, NF-κB, β-catenin, and HIF1α, all of which are well-evidenced regulators of the ABCB1 gene, but data are lacking for their regulation by Notch signaling in chemoresistant cancer associated with ABCB1." (PMID 35582031, 2021). "Entrapment of ATP-binding cassette transporter superfamily B member 1 (ABCB1) substrate doxorubicin into liposomes can increase drug uptake and enhance its intracellular distribution within cancer cells, especially ABCB1-expressing cancer cells." (PMID 34032937, 2021). "The cytotoxic potency of pLAn-SS-CTX NPs was also assessed in two paclitaxel-resistant cancer cell lines (i.e., A549/PTX and HeLa/PTX cells), both of which were characterized by high levels of P-glycoprotein (P-gp, encoded by ABCB1 gene) using western blot analysis." (PMID 33754053, 2021). "Therefore, blocking or inactivating transmembrane proteins, such as multidrug resistance protein 1 (MDR1, also known as P-gp and ABCB1) and MDR-associated protein 1 (MRP1/ABCC1), provides potential cancer therapies targeting MDR." (PMID 33669877, 2021). "Taken together, our study revealed that the drug transport mediated by ABCB1 or ABCG2 represents a novel mechanism for acquired resistance to citarinostat in human cancer cells; therefore, combination therapies will need to be tested to overcome this clinical problem in the future." (PMID 33807514, 2021). "This might suggest that IBC was a substrate of ABCB1 protein and that inhibition of the function of the transporter caused more IBC to stay inside cancer cells, thus reducing the survival rate of MDCK-MDR1 cells." (PMID 34361789, 2021). "For instance, cancer cells expressing high SLFN11 but with high expression of the drug efflux genes ABCB1 (encoding P-glycoprotein) are unlikely to respond to doxorubicin." (PMID 34572827, 2021). "Among them, ABCB1 (P-glycoprotein; P-gp, MDR1), ABCC1 (multidrug resistance-associated protein 1; MRP1), and ABCG2 (breast cancer resistance protein; BCRP, mitoxantrone resistance protein; MXR) are the major transporters involved in MDR, in cancer cells." (PMID 34830383, 2021). "The subgroup of ABCs mostly involved in cancer cell resistance to taxanes is ABCB1." (PMID 33802861, 2021). "Nowadays, the largest challenge for cancer drug treatment is MDR initiated by the elevation of the ATP-binding cassette (ABC) efflux transporters, including P-glycoprotein (P-gp/ABCB1), multidrug resistance-associated protein 1 (MRP1/ABCC1) and breast cancer resistance protein (BCRP/ABCG2)." (PMID 34026649, 2021). "Interestingly, GCS overexpression in cancer has been shown to correlate with ABCB1 expression, and increased ABCB1 correlates with increased complex GSLs in drug-resistant cells." (PMID 34597626, 2021).
cancer (continued). "This combination therapy curtailed cellular GSH levels by ABCB1 inhibition, therefore, apigenin as a potential adjuvant to anti-cancer treatment may overcome ABCB1-mediated drug resistance in cancer." (PMID 34715860, 2021). "High transport capacity is attributed to increased expression of MDR‐associated protein (MRP), P‐glycoprotein 1 (P‐gp) encoded by the MDR1 gene (also known as ABCB1), low‐density lipoprotein receptor‐related protein (LRP), and breast cancer resistance protein (BCRP) in cancer." (PMID 34766149, 2021). "Studies have reported that ABCB1/MDR1 gene SNPs may modulate the incidence of cancer rate or induce resistance to IM." (PMID 33129240, 2021). "These pathways also drive and maintain cancer cell stemness, for which ABCB1 is used as a marker." (PMID 35582031, 2021). "Recently, it has been reported that ABCB1 corresponds to trigger the development of chemo drug resistance, thus, it seems that ABCB1 down-regulation could be an effective strategy in sensitizing cancer cells to different chemotherapies." (PMID 34715860, 2021). "Furthermore, findings from a more recent trial of doxorubicin in combination with the ABCB1-modulating nilotinib showed the benefits of including a kinase inhibitor in combination therapy against multidrug-resistant cancers." (PMID 34502348, 2021). "In addition, olmutinib was also evaluated for multidrug reversal activity in cancer cell lines overexpressing ABCB1, ABCG2, or ABCC1 transporters." (PMID 34771085, 2021). "Detection of ABCB1 expression in EVs with liquid biopsy could therefore serve as an important biomarker of cancer treatment resistance." (PMID 33995103, 2021). "Combination of erdafitinib and a substrate of ABCB1 could improve the therapeutic effect for drug resistant cancers which overexpress ABCB1 transporter." (PMID 32670878, 2020). "ABCB1 overexpression is known to contribute to multidrug resistance (MDR) in cancers." (PMID 32670878, 2020). "Notably, previous studies have demonstrated strong interactions between certain TKIs and ABCB1 and/or ABCG2, resulting in the resensitization of multidrug-resistant cancer cells overexpressing ABCB1 or ABCG2." (PMID 31941029, 2020). "This phenomenon could be related to the increased expression of ABCB1 and ABCG2 in resistant variants of A2780 cancer cell line." (PMID 31991882, 2020). "Our findings that ABCB1 was associated with favourable survival in multiple cancers emphasizes the need for further studies to clarify whether ABCB1 should be targeted for cancer therapy." (PMID 33202946, 2020). "At the substrate-binding pocket of ABCB1 transporter, RN486 may supersede other anti-cancer drugs that are substrates of ABCB1 resulting in stimulation of ATPase activity." (PMID 32984343, 2020). "The development of multidrug resistance (MDR) in cancer patients driven by the overexpression of ATP-binding cassette (ABC) transporter ABCB1 or ABCG2 in cancer cells presents one of the most daunting therapeutic complications for clinical scientists to resolve." (PMID 31941029, 2020). "The ABCB1 is a drug transporter involvedin imparting cancer cells with resistance to chemotherapy." (PMID 33095554, 2020). "Consequently, ABCB1- and ABCG2-overexpressing cancer cells are less susceptible to treatment with these RTKs inhibitors." (PMID 32466597, 2020). "The present study evaluates if erdafitinib could reverse MDR mediated by ABCB1 in drug resistant cancer cells." (PMID 32670878, 2020). "We used two ABCB1-overexpressing cancer cell lines, KB-C2 and SW620/Ad300." (PMID 33519482, 2020). "In contrast, recent studies have demonstrated that several FDA-approved therapeutic agents such as osimertinib and midostaurin exhibited an inhibitory effect on ABCB1-mediated drug efflux, thus resensitizing ABCB1-overexpressing multidrug-resistant cancer cells to cytotoxic anticancer agents." (PMID 32466597, 2020).
cancer (continued). "Furthermore, the tests on combination with anticancer drugs that are ABCB1 or ABCG2 substrates, showed that peptide XH-14C potentiates the cytotoxicity of paclitaxel and doxorubicin in ABCB1-overexpressing cancer cells." (PMID 32707710, 2020). "ABCB1 gene polymorphism and ABCG2 upregulation may be responsible for the resistance of NPC cancer stem cells to chemotherapeutic drugs; tumour suppressor gene IRF6 kills cancer stem cells in NPC by targeting the ABCG2 gene." (PMID 32595725, 2020). "In addition, tumors engage various efflux transport systems (for instance, ATP-binding cassette sub-family B member 1 (ABCB1) gene, which extrude drugs from cancer cells)." (PMID 33322507, 2020). "Thus, it is unlikely that saptinib reverses the drug resistance of ABCB1 overexpressing cancer cells by altering the expression of the ABCB1 protein." (PMID 33163405, 2020). "Notably, inhibition of leptin signaling significantly reduced ABCB1 gene expression, which is well known to have high specificity for the elimination of paclitaxel from cancer cells." (PMID 32471192, 2020). "In this study, we revealed that overexpression of ABCB1 can render cancer cells resistant to GSK-1070916, which may challenge its therapeutic effect in clinical setting." (PMID 33519482, 2020). "With regard to the effects of “pharmaceutical” therapy on cancer survival, we found that the overall survival rate from cancer patients with mutated ABCB1 (n = 479) was not statistically different from those with unmutated ABCB1 control (n = 4,198)." (PMID 34541464, 2020). "Because the inclusion of an ABCB1 inhibitor can minimize the drug resistance, the combination of GSK-1070916 with ABCB1 inhibitor may provide additional benefit to cancer patients with high tumor ABCB1 expression." (PMID 33519482, 2020). "The spectrum of anti-cancer drugs ABCG2 confers resistance to overlaps with that of ABCB1." (PMID 33066132, 2020). "Thus, the ABCB1 transporter represents a potential therapeutic target for the treatment of MDR in cancers." (PMID 33163405, 2020). "Knowing that direct inhibition of the drug efflux function of ABC transporters remains the most effective approach to resensitize multidrug-resistant cancer cells to chemotherapeutic drugs, tremendous efforts have been invested into developing novel synthetic inhibitors of ABCB1 and ABCG2." (PMID 31941029, 2020). "Overexpression of ABCB1, ABCC1, and/or ABCG2 is a major cause of MDR in cancer." (PMID 33066132, 2020). "The sapitinib-induced reversal of MDR to paclitaxel and doxorubicin in SW620/Ad300 cancer cells could also result from a decrease in vitro in the number or density of ABCB1 transporter present in the cancer cell membrane." (PMID 33163405, 2020). "The mechanism of activation may also depend on the state of the ABCB1 promoter in different cancers and their cells of origin." (PMID 33167906, 2020). "The increase in ABCB1 expression has long been known to correlate with drug resistance in cancer." (PMID 32340269, 2020). "Therefore, we first examined the cytotoxicity of erdafitinib in multiple human multidrug-resistant cancer cell lines that overexpress ABCB1 or ABCG2 as well as in the corresponding drug-sensitive parental cancer cell lines." (PMID 32466597, 2020). "Overall, our results with sapitinib, as well as those obtained with other quinazoline-based EGFR inhibitors, suggest that these compounds may have the potential to treat MDR in certain cancers that overexpress ABCB1 transporter." (PMID 33163405, 2020). "This study identified a promising therapeutic strategy and may provide a potential clinical direction on overcoming ABCB1-mediated MDR in cancers." (PMID 32707710, 2020). "In conclusion, the results of this in vitro study indicate that sapitinib completely reverses the resistance of SW620/Ad300 and HEK293/ABCB1 cells overexpressing ABCB1 transporter to the anti-cancer drugs, paclitaxel and doxorubicin, which are ABCB1 substrates." (PMID 33163405, 2020).